PON1 (paraoxonase 1)
Diseases named in the same sentence as PON1 in open-access papers (continued):
Sharing a sentence is not in itself a finding about the gene and the disease.
cardiovascular disease (continued). "Genetic common variants that impair PON1 expression or enzymatic efficiency have been linked to increased oxidative burden, endothelial dysfunction, and a greater susceptibility to age-related conditions such as cardiovascular disease and metabolic syndrome." (PMID 40710578, 2025). "Plasma LCAT and PON-1 may serve as independent markers or complement other established cardiovascular disease markers to discriminate the risk of ASCVD when it is unclear." (PMID 39114750, 2024). "Association of PON1 activity with risk factors for cardiovascular disease in patients with CKD." (PMID 38982880, 2024). "A higher PON1 activity is associated with a more effective ability to remove harmful compounds that formed as a result of oxidative stress and, thus, with a lower risk of cardiovascular diseases and cancer." (PMID 36829771, 2023). "According to the study looking at the impact of gender on PON1, it was reported that females had significantly higher PON1 arylesterase and lactonase activities compared with the male participants and that gender had a strong impact on the contribution of PON1 to cardiovascular disease risk." (PMID 37545608, 2023). "Thus, PON1 polymorphism is of considerable interest due to its possible association with a number of diseases such as cardiovascular disease, carotid atherosclerosis, Parkinson, panic disorder, multiple sclerosis and Alzheimer’s disease." (PMID 36296373, 2022). "Indeed, several investigations have been previously focused on the relationship between PON-1 single nucleotide polymorphisms (SNPs) and cardiovascular disease (CVD), including CAD." (PMID 35308142, 2022). "However, studies associating genetics, dietary patterns and PON1 activity in individuals with cardiovascular disease (CVD) are scarce." (PMID 33844899, 2021). "Based on the activity levels of PON1, these findings may be important in the diagnosis of women who are more susceptible to developing cardiovascular diseases, taking into account the association between serum PON1 levels and CVD." (PMID 34762786, 2021). "Genotyping PON1 SNVs may help argue HD smokers harboring the rs705379 TT genotype or T allele and non-smokers possessing the rs662 G allele for prevention against cardiovascular diseases." (PMID 34593900, 2021). "In conclusion, RA is associated with deficiency of PON1 activity and increased protein N-homocyseinylation which may contribute to accelerated development of cardiovascular diseases." (PMID 32967340, 2020). "In conclusion, our study suggests that sex might chiefly influence PON1 activity and its contribution to cardiovascular disease risk." (PMID 31138960, 2019). "Here, we assessed whether low serum PON1 activity associates with incident cardiovascular disease (CVD) in subjects with high levels of high-density cholesterol (HDL-C) and C-reactive protein (CRP), a marker of low-grade systemic inflammation." (PMID 31480611, 2019). "PON-1 polymorphisms seem also to affect the atherosclerotic process and cardiovascular disease." (PMID 31052559, 2019). "The inhibitory mechanism of MeHg on PON1 has been hypothesized to be involved in the development of cardiovascular disease, potentially explaining epidemiological associations with MeHg35." (PMID 28325913, 2017). "Moreover, significant decrease of PON1 activity confirmed the high risk of cardiovascular diseases in smokers." (PMID 27437027, 2016). "Total PON1 plasmatic activity is negatively related to increased risk for cardiovascular disease." (PMID 27812605, 2016). "Allele frequencies for PON1 gene that influence enzyme concentration as well as activity differ greatly among ethnic groups and data from several studies showed ethnic variations in the interpretation of cardiovascular disease (CVD) associated with PON1 polymorphisms." (PMID 25551104, 2014). "The combination of PON1 phenotype and environmental cadmium and lead exposure may play a role in an individual's risk for cardiovascular disease." (PMID 24682159, 2014).
cardiovascular disease (continued). "PON1 phenotype may represent the contribution that genetics makes towards determining individual cardiovascular disease risk." (PMID 24682159, 2014). "Several articles support the hypothesis that lower serum PON1 activity is related to an increase in plaque formation and, consequently, to a higher risk of cardiovascular disease." (PMID 25405733, 2014). "In addition, epidemiological evidence demonstrates that low PON1 activity is associated with increased risk of cardiovascular events and is an independent risk factor for cardiovascular disease." (PMID 23251155, 2012). "If this hypothesis is true, by restoring PON1 function, there could be a possibility for a new therapeutic tool for cardiovascular diseases, with particular advantageous effects in high-risk patients, such subjects with MS." (PMID 21960992, 2012). "We are looking forward to testing whether PON1 activity as measured by this commercial kit will constitute a useful biomarker to predict the risk of cardiovascular disease in this population during the follow-up phase of the cohort study." (PMID 21543280, 2011). "The role of the PON1 Q192R polymorphism in cardiovascular diseases is still under debate." (PMID 21569287, 2011). "Therefore, PON1 has been described as a risk factor for developing cardiovascular diseases." (PMID 39408985, 2024). "The found association of medical history of premature cardiovascular disease and PON1 paraoxonase activity may emphasize the importance of genetic factors underlying CHD, because PON1 activity towards paraoxon is highly variable depending on genetic polymorphism." (PMID 30935088, 2019). "Individuals that maintained CD4+ T-cells within normal ranges and undetectable HIV-1 RNA levels, as a result of HAART, showed a restoration of the immune system function and of PON1 activity, which could lead and conduce to a lower risk for cardiovascular disease." (PMID 24719500, 2014). "Second, the lack of comprehensive data in the literature on CAE limits the interpretation of PON1 activity within the broader context of cardiovascular diseases." (PMID 40342642, 2025). "Mammalian paraoxonase-1 (PON1) is a ~ 39.45 kDa calcium-dependent hydrolytic enzyme with potential therapeutic applications in chemical defense and cardiovascular disease." (PMID 40457011, 2025). "PON1 protects against cardiovascular disease by preventing LDL oxidation, while the variant NM_000446.7 (PON1):c.575A>G p.Gln192Arg (rs662) affects enzyme activity, with the G allele linked to altered paraoxonase function and potential cardiovascular risk." (PMID 40710578, 2025). "Research on the PON1 gene has mainly focused on cardiovascular diseases, with relatively limited studies in RA at present." (PMID 40183079, 2025). "Our findings suggested that PON1 is a potential biomarker of cardiovascular disease severity in Caribbean Hispanics." (PMID 39408985, 2024). "Numerous clinical studies have shown an association between polymorphisms of the PON1 and TRIB1 genes and various cardiovascular diseases." (PMID 39062650, 2024). "Taken together, our results provide further evidence in favor of the role of PON1 as a potential predictive biomarker of cardiovascular disease severity in Caribbean Hispanics." (PMID 39408985, 2024). "Low PON1 expression/activity is accompanied by increased oxidative stress and predicts adverse outcomes in cardiovascular disease (CVD), diabetes, neurological disease, and cancer." (PMID 39594433, 2024). "Paraoxonase 1 (PON1) is an HDL-associated enzyme involved in reducing lipid peroxide accumulation on LDL, suggestive of a protective role against cardiovascular disease." (PMID 37818163, 2023). "Other biomarkers associated with cardiovascular disease risk include the acute phase protein serum amyloid A1 (SAA1) and the antioxidant protein serum paraoxonase/arylesterase 1 (PON1), both situated on high-density lipoprotein as well." (PMID 38054074, 2023).
cardiovascular disease (continued). "Recent studies have shown PON enzymes, specifically PON-1, play an essential role as anti-inflammatory and anti-oxidative stress modulators against foam cell formation in cardiovascular diseases." (PMID 37108044, 2023). "PON1 has been extensively investigated in the context of cardiovascular disease in mouse models and in humans." (PMID 37175471, 2023). "Vast scientific evidence has postulated PON1 as a beneficial factor in the setting of cardiovascular disease." (PMID 36118876, 2022). "The CC- 108 genotype was significantly correlated with the incidence of cardiovascular disease, while all three PON1 activities were reduced in the disease group." (PMID 36118876, 2022). "Lower PON1 is associated with low thiols, higher CRP, lower HDL3, and adverse future cardiovascular disease (CVD) outcomes." (PMID 35624764, 2022). "Understanding the physiological mechanisms which enhance the enzyme activity, affect epigenetic regulation and modify the signaling pathways of PON1 transcriptional factors is crucial for the development of new targeted therapies for cardiovascular diseases." (PMID 35889799, 2022). "PON1 isoforms are known to have a broad range of roles including being involved in mediating against cardiovascular diseases, drug metabolism and bacterial infections." (PMID 36296373, 2022). "Evidence suggests a potential role for PON-1 in mediating cardiovascular disease (CVD) in patients with CKD." (PMID 35624764, 2022). "Reductions in PON1 enzymatic activity in patients with cardiovascular disease have been observed in numerous studies." (PMID 34331945, 2021). "Although some reports have partially investigated this parameter in patients with cardiovascular disease, few studies have evaluated serum PON1 activity in respiratory diseases." (PMID 31655531, 2020). "Better evaluation of PON1 genetic variability, concentration or activity is therefore needed to improve the understanding of PON1 role in cardiovascular disease and especially in treatment-related cardiotoxicity." (PMID 33425072, 2020). "Taking into account a protective role of PON1 in cardiovascular diseases, we found it also necessary to evaluate the influence of these vanadium complexes on this parameter." (PMID 28529953, 2017). "It is well established that reduced serum PON1 activity in CKD contributes to the increased burden of cardiovascular disease in this patient group, being more prominent in end-stage CKD." (PMID 29333213, 2017). "In this study, we found that the serum level of PON1 declined considerably in YDH syndrome rats (p = 0.0052), which was consistent with the PON1 alterations in cardiovascular disorders, cancer, and acute influenza infection." (PMID 27843478, 2016). "Increased activity of paraoxonase 1 induces an increase in the concentration of HDL in serum, confirming that increased paraoxonase 1 activity leads to less cardiovascular disease in humans." (PMID 28357199, 2016). "All these findings show complexity of the link between PON1 SNPs and cardiovascular disease or subsequent mortality." (PMID 25155309, 2016). "One of the key actions of the Mediterranean diet is the prevention of cardiovascular diseases, which can be promoted in part by increased PON1 activity." (PMID 26024295, 2015). "In line, serum antioxidant activity of PON1 is an important factor in cardiovascular diseases, providing protection from oxidative stress and lipid peroxidation." (PMID 25276769, 2014). "Human serum paraoxonase 1 (PON1) is a key antioxidant enzyme that seems to play a role in carcinogenesis and cardiovascular disease." (PMID 24682159, 2014). "Other PON1 and PON2 polymorphisms (M55L, C-108T, R-160G, G-162A from PON1 and S311C and A148G from PON2) have been associated with cardiovascular disease." (PMID 25405733, 2014).
cardiovascular disease (continued). "Others have shown an increased activity of PON1 in individuals who maintains a physical activity routine, which is a protective factor against cardiovascular disease by improving the quality of their HDL." (PMID 23799909, 2013). "In light of the potential importance of PON1 in preventing cardiovascular disease/events, these novel loci merit further investigation." (PMID 22577559, 2012). "Thus, dietary and pharmacological inducers of PON1 may decrease cardiovascular disease risk." (PMID 22304296, 2012). "Here, we evaluated the relationship between PON1 activity and another known predicting factor for cardiovascular diseases, the LDL levels." (PMID 22721254, 2012). "Paraoxonase 1 (PON1) is a HDL-associated esterase/lactonase and its activity is inversely related to the risk of cardiovascular diseases." (PMID 22738670, 2012). "The role of PON1 in development of cardiovascular disease has drawn considerable attention in recent years." (PMID 20535264, 2010). "Methods using the non-physiological paraoxon as substrate have traditionally been used to measure PON1 activities, the levels of which have been proposed as indicators in the prediction of cardiovascular disease." (PMID 20334696, 2010). "The effect of FF on the decrease in PON-1 activity is an important new finding that could contribute to explaining the inability of FF to reduce cardiovascular disorders." (PMID 39857794, 2025). "Considering this role in cardiovascular diseases and its antioxidant properties, PON1 activity may be a valuable biomarker in predicting coronary artery ectasia (CAE), whose pathogenesis has not yet been fully elucidated." (PMID 40342642, 2025). "Paraoxonase 1 (PON1), a high-density lipoprotein (HDL)-associated enzyme, is increasingly recognized for its crucial role in protecting against oxidative stress and inflammatory processes, particularly in the context of cardiovascular diseases." (PMID 41049124, 2025). "Pearson bivariate correlation between lecithin-cholesterol acyltransferase, paraoxonase-1 and conventional lipid profile of atherosclerotic cardiovascular diseases patients at Lagos State University Teaching Hospital, Lagos, Nigeria, between March 2022 and March 2023." (PMID 39114750, 2024). "The Mediterranean diet, recommended for the prevention of cardiovascular diseases, has resulted in higher postprandial PON1 activity, which might be the result of using extra virgin olive oil." (PMID 38474211, 2024). "The results presented herein indicate that PON1 could potentially serve as a useful predictive biomarker of the cardiovascular disease’s severity in Caribbean Hispanic patients suffering from ACS or stable CAD." (PMID 39408985, 2024). "This may suggest that PON1 in poor responders has a reduced ability to act as an antioxidant enzyme, further increasing the severity of cardiovascular disease." (PMID 39408985, 2024). "The low abundance of PON1 in the poor responders could also be a direct consequence of the severity of cardiovascular diseases." (PMID 39408985, 2024). "Furthermore, evidence supporting the implication of reduced PON1 activity in the incident of cardiovascular disease in CKD patients, is also examined." (PMID 38982880, 2024). "Regarding human studies, a significant increase in PON1 activity was observed in hemodialyzed patients receiving tea catechins, known for their antioxidant function and preventive properties from cardiovascular diseases, and in hypercholesterolemic subjects as a result of anthocyanin intake." (PMID 36833509, 2023). "Furthermore, a subset of antioxidant enzymes, the paraoxonases (PON), deserve special attention due to abundant clinical evidence regarding reduced serum PON1 activity in CKD as a contributor to the increased burden of cardiovascular disease." (PMID 37760075, 2023).
cardiovascular disease (continued). "Moreover, negative correlations have been found between miRNA levels (e.g., miR-92a, miR-486, and miR-122) with the PON1 enzymatic activity and the development of cardiovascular diseases." (PMID 35453382, 2022). "The significant improvement in the activity of PON-1 sheds a light to the promising therapeutic effectiveness of metformin + lycopene for the management of metabolic complications resulting from oxidative stress, especially cardiovascular diseases." (PMID 36500596, 2022). "Many studies have shown the important role of PON-1 in cardiovascular disease (CVD)." (PMID 36140402, 2022). "More detailed and extensive research on the mechanisms of PON1 modulation by carotenoids may lead to the development of new targeted therapies for cardiovascular diseases." (PMID 35889799, 2022). "Carotenoids supplementation may help modulate PON1 antioxidant and anti-inflammatory effects and increase the enzyme potential to preserve lipoproteins from oxidation and prevent cardiovascular diseases." (PMID 35889799, 2022). "Therefore, a consensus was formed that PON1 concentration and activity are higher predictors of cardiovascular disease than the PON1 genotype alone." (PMID 35889799, 2022). "Results of genotyping PON1 SNVs may help argue HD patients for prevention against cardiovascular diseases by rejecting or reducing cigarette smoking." (PMID 34593900, 2021). "Given shared catalytic residues, it is not surprising that reduced PON1 activity measured using all four substrate activities is associated with cardiovascular disease." (PMID 34331945, 2021). "Almost four decades later, a new role of PON1, in preventing the oxidation of low-density lipoproteins (LDLs) and HDLs, was reported, generating an increased interest in the study of PON1 in relation to cardiovascular disease among the scientific community." (PMID 33287338, 2020). "PON1 activity is inversely correlated with cardiovascular diseases." (PMID 33425072, 2020). "Previous studies have shown that PON1 is an independent risk factor for cardiovascular disease; however, the exact antioxidant mechanism of PON1 is not yet known." (PMID 31655531, 2020). "Therefore, further investigations are needed to clarify the role of oxidative stress markers, including MDA and PON-1, in the pathogenesis of peripheral ED and increased cardiovascular disease in RA patients." (PMID 32854225, 2020). "The clinical significance of PON1 has been evaluated mainly in cardiovascular diseases." (PMID 30886652, 2019). "However, based on the current findings, future studies can be designed to screen the population for PON1 and further investigate its role in cardiovascular diseases." (PMID 30044465, 2018). "Finally, a subset of antioxidant enzymes, the paraoxonases (PON), deserves special attention due to abundant clinical evidence accumulated regarding reduced serum PON1 activity in CKD as a contributor to the increased burden of cardiovascular disease." (PMID 29333213, 2017). "Meta-analyses indicated a correlation between risk of cardiovascular disease and PON1 activity among people independent of age or ethnicity." (PMID 28529953, 2017). "The PON1 Q192R polymorphism affects the catalytic efficiency and is considered a risk factor for pesticide intoxication and cardiovascular disease (CVD) but the association is not consistent between individuals or populations." (PMID 29430251, 2017). "Paraoxonase-1 (PON1), a major antioxidant, is regarded as a cardiovascular protective factor and it is well documented that the activity of this enzyme is reduced in patients with cardiovascular diseases." (PMID 27313824, 2016). "PON1 has been extensively studied as a risk factor for cardiovascular disease independent of lipoprotein concentrations." (PMID 22701797, 2012). "The lesson learned from the PON1 role in cardiovascular disease is of utmost relevance." (PMID 22536488, 2012). "PON1 rs3917542 has been associated with cardiovascular diseases but not cancer." (PMID 40149317, 2025).